GK2 (glycerol kinase 2)
Description:
Key enzyme in the regulation of glycerol uptake and metabolism. Essential for male fertility and sperm mitochondrial sheath formation (By similarity). Required for proper arrangement of crescent-like mitochondria to form the mitochondrial sheath during spermatogenesis (By similarity). Can induce mitochondrial clustering through interactions with PLD6 and up-regulation of phosphatidic acid synthesis in the mitochondria.
Synonyms: GKP2; GKTA
Tractability: Antibody: UniProt predicts a signal peptide or a membrane-spanning region. PROTAC: ubiquitination databases record sites on it; its protein half-life has been measured.
Gene: Protein-coding gene on chromosome 4 (79,406,361 to 79,408,228, reverse strand). Ensembl gene ENSG00000196475.
Subcellular location: Mitochondrion outer membrane; Cytoplasm
Pathways (Reactome):
Metabolism: Triglyceride biosynthesis
Gene Ontology:
Molecular function: protein binding; glycerol kinase activity; kinase activity; phosphotransferase activity, alcohol group as acceptor
Biological process: flagellated sperm motility; glycerol-3-phosphate biosynthetic process; sperm mitochondrial sheath assembly; spermatogenesis; triglyceride metabolic process; carbohydrate metabolic process; glycerol catabolic process; glycerol-3-phosphate metabolic process
Cellular component: extracellular exosome; mitochondrion; sperm midpiece; mitochondrial outer membrane; sperm mitochondrial sheath; cytoplasm
Genetic constraint (gnomAD): Loss-of-function variants: 15 observed, 16.3 expected, observed/expected ratio (o/e) 0.92, 90% interval 0.62 to 1.41. The upper end of that interval is the gene's LOEUF score, 1.41, which puts it in group 5 of 6, group 1 being the genes least tolerant of losing a copy. Missense variants: 636 observed, 691.97 expected, observed/expected ratio (o/e) 0.92, 90% interval 0.86 to 0.98. Synonymous variants: 222 observed, 236.9 expected, observed/expected ratio (o/e) 0.94, 90% interval 0.84 to 1.05.
Homologues: Orthologues: chimpanzee GK2 (99% identical), macaque GK2 (98% identical), dog GK2 (85% identical), mouse Gk2 (85% identical), rabbit GK2 (82% identical), rat Gk2 (81% identical), tropical clawed frog gk (80% identical), pig GK2 (73% identical), zebrafish GK2 (72% identical), Drosophila melanogaster Gk2 (47% identical), Caenorhabditis elegans R11F4.1 (43% identical), Drosophila melanogaster CG8298 (40% identical). Paralogues in human: GK (88% identical), GK3 (88% identical), GK5 (30% identical), FGGY (19% identical), XYLB (16% identical), SHPK (15% identical).
Diseases named in the same sentence as GK2 in open-access papers:
GK2 is named in the same sentence as 8 diseases in open-access papers, as found by Europe PMC text mining. Sharing a sentence is not in itself a finding about the gene and the disease. The quoted sentences say what the papers report.
Infertility (4 papers, 2017 to 2025). "Becausesperm motility is also important for transiting through the UTJ, the decreased sperm motility due to morphological abnormality of spermatozoa can be the cause of infertility of Gk2 KO mice." (PMID 30662012, 2019). "To probe the causes of infertility and reproductive defects in Gykl1 and Gk2 KO mice, we carried out computer-assisted spermatozoa analysis (CASA) to document spermatozoa motility, including curvilinear velocity, straight-line velocity, and amplitude of lateral head movement in the mutant mice." (PMID 28852571, 2017). "•ARMC12 interacts with GK2 (and other mitochondrial proteins, such as VDAC), which is required for mitochondrial sheath formation.•Absence of ARMC12 causes abnormal mitochondrial coiling around the flagellum, resulting in reduced motility and infertility." (PMID 41008556, 2025). "•GK2 seems to interact with Kastor and Polluks, two sperm-specific polypeptides that are directly connected with VDAC proteins.•VDAC3-deficient mice show reduced sperm motility and consequent infertility." (PMID 41008556, 2025). "Additionally, intracytoplasmic spermatozoa injection (ICSI) of Gykl1- or Gk2-KO spermatozoa led to normal offspring, suggesting that their infertility may be accounted to defects in fertilization." (PMID 28852571, 2017). "When mated with wild-type C57BL/6J females, Gykl1−/− and Gk2−/− males appeared infertile, and significant reduction (50%) in pregnancy rates was noted for the Gykl1+/− mice." (PMID 28852571, 2017).
male infertility (4 papers, 2017 to 2025). The inability of the male to effect fertilization of an ovum after a specified period of unprotected intercourse. "In line with this, an association between mitochondrial dysfunctionality and male infertility as a result of a diminished sperm motility has been reported for several knockout models (VPS13A, Tppp2, Gykl1, and Gk2)." (PMID 34765607, 2021). "Regarding the observation of decreased GK2 in teratozoospermia, the Gykl1 or Gk2 KO mice did show abnormalities in morphology defected spermatozoa, which again raised the possible link between male infertility and Gyk-like proteins." (PMID 28852571, 2017). "In Gk2-7/-7 mice, the unprocessed form ofADAM3 in testicular spermatozoa and the processed form in epididymal spermatozoa were detected normally.These results indicate that Gk2-7/-7 KO mice show male infertility due to an impairment of sperm passage through the UTJ despite proper ADAM3 processing." (PMID 30662012, 2019). "Glycerol kinase 2 (GK2), a testis-specific gene involved in mitochondrial function and sperm motility, has emerged as a potential biomarker, with alterations in its expression being associated with impaired spermatogenesis, motility, and, consequently, male infertility." (PMID 41008556, 2025). "Furthermore, deletion of either Gykl1 or Gk2 in mice, by CRISPR/Cas9-mediated gene knockout (KO), impacted mitochondrial morphology and mitochondrial ATP production as well as midpiece and sperm tail integrity in spermatozoa, compromising spermatozoa motility and leading to male infertility." (PMID 28852571, 2017).
asthenozoospermia (3 papers, 2017 to 2022). "Regarding that increased GK2 may correlate to asthenozoospermia, we suspected that increased GK2 could induce abnormal mitochondrial function or ATP deficiency then contribute to asthenozoospermia." (PMID 28852571, 2017). "Notably, dysregulated GK2 expression has been linked to teratozoospermia and asthenozoospermia." (PMID 28852571, 2017). "Also, the unregulated ATP level we observed indicates a potential mechanism of GK2-related asthenozoospermia that could be partially caused by defects in mitochondrial ATP production." (PMID 28852571, 2017). "Interestingly, decreased GK2 mRNA expression in males with teratozoospermia and increased GK2 protein levels in asthenozoospermia patients have also been reported, suggesting regulated expression of GK2 may be a key factor in male fertility." (PMID 28852571, 2017).
teratozoospermia (1 paper, 2017). "Defects in mitochondrial sheath and damages in sperm tail in Gykl1 or Gk2 KO mice mimic the case in GK2-related teratozoospermia." (PMID 28852571, 2017).
GK2 also shares sentences with these, for which no sentence is quoted: breast carcinoma (1 paper); Huntington disease (1); infection (1); oligospermia (1).